FGFR2 (fibroblast growth factor receptor 2)
Diseases named in the same sentence as FGFR2 in open-access papers (continued):
Sharing a sentence is not in itself a finding about the gene and the disease.
Apert syndrome (continued). "A mutation of Fibroblast Growth Factor Receptor 2 (FGFR2) gene causes the autosomal dominantly inherited Apert syndrome." (PMID 34633507, 2022). "The genetic causes of Apert syndrome are variants affecting the fibroblast growth factor receptor 2 (FGFR2) gene." (PMID 35997397, 2022). "FGFR2 gain-of-function mutations contribute to Apert syndrome, Beare–Stevenson syndrome, Crouzon syndrome, Pfeiffer syndrome and bent bone dysplasia, each involving suture fusion." (PMID 35451466, 2022). "Mosaic germline mutations in the FGFR2 gene have been associated with Apert syndrome and nevus comedonicus, two illnesses that are accompanied by acneiform lesions." (PMID 34829964, 2021). "Diagnosis is established in a patient clinically or by genetic testing resulting in the identification of heterozygous pathogenic variant of the FGFR2 and the presences of clinical features consistent with Apert syndrome." (PMID 33248465, 2020). "Syndromes associated with cleft palate include those arising from mutations in FGFR1-3; e.g. Apert syndrome (FGFR2), Muenke syndrome (FGFR3), Crouzon syndrome (FGFR2, FGFR3) and Hartsfield syndrome (FGFR1)." (PMID 31613912, 2019). "At least seven mutations in fibroblast growth factor receptor 2 (FGFR2) gene have been found to cause Apert syndrome." (PMID 31387623, 2019). "In a fetus with bilateral syndactyly of hands and feet and corpus callosum agenesis (family 3), the molecular diagnosis of Apert syndrome was made by identifying a known pathogenic de novo variant in FGFR2." (PMID 30679815, 2019). "For example, a single mutation in a gene called FGFR2 causes malformations in the head, the heart and the limbs in a rare disease called Apert syndrome." (PMID 30234486, 2018).
Apert syndrome (continued). "Overall, the high correlation between the shape of the limb and the Dusp6 expression domain provides further evidence that altered Fgf expression resulting from the Fgfr2 mutation is strongly associated with limb defects in Apert syndrome." (PMID 30234486, 2018). "We identified subtle but significant differences in the gene expression of a downstream target of a Fgfr2 mutation associated with Apert syndrome, demonstrating that these mouse models can further our understanding of limb defects in the human condition." (PMID 30234486, 2018). "Some of these features can also be seen in patients with Apert syndrome (AS), which is also caused by mutations in FGFR2." (PMID 28069589, 2017). "Despite these advances in the understanding of FGFR2 mutations, the molecular mechanisms underlying pathogenesis of Apert syndrome still remain poorly understood." (PMID 25693202, 2015). "Within each model for Apert syndrome, mice carrying an Fgfr2 mutation exhibited statistically significant differences in late prenatal skull growth relative to unaffected littermates for most of the craniofacial regions." (PMID 24580805, 2014). "Confidence intervals for local effects of the two Fgfr2 Apert syndrome mutations at E17.5 reveal differential characteristics of mutation-driven shape change." (PMID 24580805, 2014). "Here we provide a comparative analysis of craniofacial suture closure and growth pattern in two mouse models for Apert syndrome, each carrying a mutation in FGFR2 that together account for 99% of all known cases of Apert syndrome." (PMID 24580805, 2014). "Apert syndrome is an autosomal dominantly inherited disorder caused by missense mutations in fibroblast growth factor receptor 2 (FGFR2)." (PMID 25003957, 2014).
Apert syndrome (continued). "The two Apert syndrome mutations increase FGFR2's FGF ligand binding affinity and alter ligand specificity." (PMID 22359510, 2012). "There is considerable evidence that the two common Apert syndrome FGFR2 mutations confer a germline advantage on human SrAp." (PMID 22359510, 2012). "Here we show that besides morphological dysmorphologies (premature suture fusion, midfacial hypoplasia, and cleft palate), Apert syndrome Fgfr2 mutations affect morphological integration patterns within the skull by increasing its magnitude." (PMID 22053191, 2011). "For example, positive selection of sperm with mutations in FGFR2 in the male germline is thought to contribute to the paternal age effect in Apert syndrome." (PMID 22171155, 2011). "We present a child with Apert syndrome in whom routine genetic testing had excluded the FGFR2 missense mutations commonly associated with this disorder." (PMID 21943124, 2011). "Apert syndrome is almost always caused by a spontaneous mutation of paternal origin in one of two nucleotides in the fibroblast growth factor receptor 2 gene (FGFR2)." (PMID 19593369, 2009). "Apert syndrome is caused by a mutation of the fibroblast growth factor receptor 2 (FGFR2) gene." (PMID 39152701, 2024). "Activating germline variants in FGFR2 have been linked to several autosomal dominantly inherited congenital malformation syndromes such as Apert syndrome (MIM 101200), Crouzon syndrome (MIM 123500), Jackson–Weiss syndrome (MIM 123150), and Pfeiffer syndrome (MIM 101600)." (PMID 38265560, 2024). "Similarly, premature fusion of the ISS (much as in Shh+/−) leads to a decrease in the full length of the skull and midface hypoplasia in a mouse model of Apert syndrome bearing an Fgfr2 mutation." (PMID 38558491, 2024). "In up to 95% of patients, Apert syndrome is due to a mutation in FGFR2." (PMID 38353121, 2024).
Apert syndrome (continued). "Another explanation could be the older paternal age, that is generally associated with AMA, can increase gene mutations in sperm, thus increase the risk of some offspring skeletal malformations like Apert syndrome caused by FGFR2 mutations." (PMID 37165329, 2023). "Apert syndrome is a rare genetic disorder caused by pathogenic variants of the FGFR2 gene." (PMID 35997397, 2022). "The mutations in FGFR2 causing Apert syndrome may trigger a variety of changes at the molecular, cellular, and tissue levels to affect the morphology of the palate." (PMID 35997397, 2022). "The FGFR2 variant occurred in a known Apert syndrome hotspot." (PMID 35346302, 2022). "Another example is the insertion of an Alu element in exon 9, or just at the beginning of exon 9, of the fibroblast growth factor receptor 2 (FGFR2) gene, which may be a cause of Apert syndrome." (PMID 35269693, 2022). "The mutations in FGFR2 causing Apert syndrome may change a signaling network in epithelial–mesenchymal interactions during palatogenesis." (PMID 35997397, 2022). "However, most individuals with Apert syndrome develop the disorder as the result of a de novo mutation in the FGFR2 gene." (PMID 34633507, 2022). "This may indicate defects in palatal bone formation caused by the pathogenic FGFR2 variant, or it could be secondary to midface hypoplasia, which is one of the features of Apert syndrome." (PMID 35997397, 2022). "Mutant mice carrying specific gain-of-function mutations in Fgfr2 provide models of Apert syndrome." (PMID 35451466, 2022). "Therefore, the alteration of the Dusp6 expression pattern between E10 and E11.5, caused by the Fgfr2 mutation, will correlate with the limb dysmorphologies associated with Apert syndrome." (PMID 30234486, 2018). "Interestingly, in human Apert syndrome (OMIM 101200) a paternal origin of the causal FGFR2 mutation was shown in more than 50 families." (PMID 28768473, 2017). "The pooled PLS analysis including all mice was used to test whether Apert syndrome Fgfr2 mutations alter the normal pattern of MI within the skull." (PMID 22053191, 2011).
Apert syndrome (continued). "In our Apert syndrome mouse models we have found that both the facial skeleton and the neurocranium are primarily affected by the Fgfr2 mutations, and that the MI patterns are conserved, but the magnitude of integration between the face and the neurocranium is increased." (PMID 22053191, 2011). "Overall, the two Fgfr2 Apert syndrome mutations produce similar morphological effects." (PMID 22053191, 2011). "In humans, Apert syndrome is caused by gain of function mutations of FGFR2." (PMID 20175913, 2010). "Namely, Apert syndrome is caused by a mutation in FGFR2 and includes phenotypic characteristics like cleft palate, hearing loss, and hypertelorism, while Crouzon syndrome is a result of FGFR2 and FGFR3 mutation, presenting with mandibular prognathism, tarsal bones’ fusion, and hearing loss." (PMID 38673496, 2024). "Moreover, FGFR2 mutations have previously been linked to bone development and growth diseases, such as Apert syndrome, a genetic syndrome characterized by untimely early fusion of the skull bones during development that displays skeletal class III malocclusion." (PMID 34884839, 2021). "Overall, the time courses showing the dynamics of limb shape and gene expression pattern changes throughout development confirmed that the Fgfr2 Apert syndrome mutation causes an aberrant overexpression of Dusp6 early in development, which could later lead to significant limb malformations." (PMID 30234486, 2018). "Our main goal is not to identify the morphological modules of the mouse skull, but to determine whether the Fgfr2 Apert syndrome mutations alter a specific pattern of skull MI and thus infer if the FGF/FGFR signaling contributes to patterns of integration of the head." (PMID 22053191, 2011). "In our reported case, the patient with Apert syndrome harbored both an oncogenic CTNNB1 variant and a pathogenic FGFR2 mutation." (PMID 40843798, 2025). "An alteration in the FGFR2 gene (fibroblast growth factor receptor 2) located on chromosome 10 results in Apert syndrome." (PMID 40261605, 2025). "Mutant mice with compromised or lost Fgfr2 function show unilateral renal agenesis, similar to patients with Apert syndrome." (PMID 38353121, 2024). "Premature fusion of cranial sutures is most often associated with Apert syndrome (FGFR2), Muenke syndrome (FGFR3), Crouzon syndrome (FGFR2), Pfeiffer syndrome (FGFR2, FGFR1), and Saethre-Chotzen syndrome (TWIST1)." (PMID 37629737, 2023). "Gain-of-function FGFR2 signaling thus adds on IGF1R and INSR signaling in puberty, enhancing the AKT-mTORC1 pathway and causing the acne in Apert syndrome and acne nevus of Munro." (PMID 37998335, 2023). "FGF10 contributes to the skeletal and visceral defects of the Apert syndrome mouse model created by deletion of Fgfr2 exon IIIc." (PMID 35997397, 2022). "The mesenchymal bone and cartilage stigmata of Apert syndrome arise via mutant FGFR2-induced upregulation of prodifferentiation p38-MAPK signaling." (PMID 34007277, 2021).